PELI1 (pellino E3 ubiquitin protein ligase 1)
Diseases named in the same sentence as PELI1 in open-access papers (continued):
Sharing a sentence is not in itself a finding about the gene and the disease.
congenital malformations (1 paper, 2020). "Smaducin 6 inhibited Peli1-mediated inflammatory cytokine responses and cell death in placental trophoblasts and hNSCs, and attenuated congenital malformations in mice." (PMID 32544190, 2020). "Third, Smaducin-6, which blocks Peli1-mediated NF-κB activation, inhibits inflammatory responses and cell death in human placental trophoblasts and hNSCs, reduces placenta inflammation, and attenuates congenital malformations in mice." (PMID 32544190, 2020).
cyst (1 paper, 2026). A sac-like closed membranous structure that may be empty or contain fluid or amorphous material. "Using doxycycline-inducible Peli1-transgenic mice, we establish that Peli1 overexpression leads to impaired renal function and facilitates cyst formation." (PMID 41786698, 2026).
emphysema (1 paper, 2019). "Both WT and Peli1−/− LPS/elastase-treated mice developed airway inflammation, illustrated by an increase in cellularity and loss of alveolar architecture consistent with emphysema." (PMID 31417543, 2019).
esophageal squamous cell carcinoma (1 paper, 2022). Esophageal squamous cell carcinoma (ESCC) is a type of esophageal carcinoma (EC) that can affect any part of the esophagus, but is usually located in the upper or middle third. "Multivariate analyses of variables associated with overall survival in patients with stage III esophageal squamous cell carcinoma of high PELI1 expression." (PMID 34738714, 2022). "Here, we observed that high expression of pellino E3 ubiquitin protein ligase 1 (PELI1) was correlated with improved prognosis in human esophageal squamous cell carcinoma stage III patients that received adjuvant radiotherapy." (PMID 34738714, 2022).
esophageal tumor (1 paper, 2022). "The results showed that Peli1 deletion significantly increased the tumorigenesis of 4‐NQO–induced esophageal tumor in mice." (PMID 34738714, 2022). "The results showed that TUNEL immunofluorescence in the Peli1‐deficient tumor tissue was significantly lower than that in the WT tumor tissue, indicating that PELI1 indeed potentiated radiotherapy‐mediated esophageal tumor cell apoptosis in vivo." (PMID 34738714, 2022). "We observed no significant accumulation of the radiotracer in the esophageal tumors of the WT and Peli1‐deficient mice before IR treatment." (PMID 34738714, 2022).
gastric tumor (1 paper, 2025). "ROC curves were generated for five cancer types—LIHC, KIRC, ESCA, COAD and gastric tumor—based on gene expression data derived from the Gene Expression Omnibus (GEO) datasets, where PELI1 exhibited differential expression levels across these malignancies." (PMID 41562077, 2025). "Moreover, ROC curve analysis identified PELI1 as a highly accurate diagnostic marker for several tumor types, including LIHC, KIRC, ESCA, COAD and gastric tumor." (PMID 41562077, 2025).
hematoma (1 paper, 2024). A hematoma is a collection of blood from a vascular structure into an extravascular space. "Intriguingly, the detection of upregulated PELI1 expression in the peri-hematoma region of ICH human brain provided us with a direction for further investigation into the relationship between TonEBP and PELI1." (PMID 38338716, 2024).
hepatocellular carcinoma (1 paper, 2025). A malignant tumor that arises from hepatocytes. "PELI1 expression was positively correlated with the IC50 of hepatocellular carcinoma investigational drug–CFI-402257." (PMID 41562077, 2025). "Furthermore, at the single-cell level in hepatocellular carcinoma, PELI1 was highly expressed in endothelial cells, myeloid cells and lymphocyte." (PMID 41562077, 2025). "Thus, our work not only reinforces the oncogenic role of PELI1 but also broadens its functional repertoire by delineating a hepatocellular carcinoma -specific mechanistic pathway." (PMID 41562077, 2025).
HIV-1 infection (1 paper, 2017). The type species of lentivirus and the etiologic agent of acquired immunodeficiency syndrome (AIDS). "The ubiquitin ligase Peli1 encoded by PELI1 inversely regulated T lymphocyte activation, whose expression level was decreased in our study, partly indicating hyperactivation of CD4+ T cells related to pathogenesis in HIV-1 infection." (PMID 28222782, 2017).
injury (1 paper, 2020). Damage inflicted on the body as the direct or indirect result of an external force, with or without disruption of structural continuity. "By using a CCI-induced neuropathic pain model, here we revealed a rapid and persistent increase of Peli1 expression in the spinal cord after nerve injury." (PMID 32171293, 2020).
myocardial ischemia (1 paper, 2025). A disorder of cardiac function caused by insufficient blood flow to the muscle tissue of the heart. "Specifically, PELI1 deletion in macrophages was found to reduce myocardial ischemia/reperfusion injury." (PMID 40124544, 2025).
polycystic kidney disease (1 paper, 2026). A usually autosomal dominant and less frequently autosomal recessive genetic disorder characterized by the presence of numerous cysts in the kidneys leading to end-stage renal failure. "Normal signaling pathways (Left) and Peli1-mediated signaling pathways in polycystic kidney disease (Right)." (PMID 41786698, 2026). "A schematic model is proposed to describe the role of Peli1 in the development of polycystic kidney diseases." (PMID 41786698, 2026).
Psoriasiform dermatitis (1 paper, 2023). A skin abnormality characterized by redness and irritation, with thick, red skin that displays flaky, silver-white patches (scales). "Mice with systemic and conditional depletion of PELI1 were protected from psoriasiform dermatitis and showed reduced IL-17A production and NFkB activation in Th17 cells." (PMID 36901778, 2023). "The inhibition of PELI1 significantly ameliorated murine psoriasiform dermatitis by reducing IL-17A production." (PMID 36901778, 2023).
psychosis (1 paper, 2023). "NPAS3, RBM38, and PELI1 were associated with the risk of AD in APOE4 (-) individuals and AD with psychosis in a European cohort." (PMID 36982982, 2023).
Renal cyst (1 paper, 2026). A fluid filled sac in the kidney. "In summary, our data indicate that TLR-driven upregulation of Peli1 facilitates renal cyst growth via S6K1 stabilization." (PMID 41786698, 2026).
testicular germ cell tumor (1 paper, 2025). A germ cell tumor arising from the testis. "Regarding MSI, PELI1 expression showed positive correlations in testicular germ cell tumors (TGCT) and LAML, whereas negative associations were observed in DLBC, uterine carcinosarcoma (UCS), KIPAN, HNSC, and KICH." (PMID 41562077, 2025).
triple-negative breast carcinoma (1 paper, 2023). An invasive breast carcinoma which is negative for expression of estrogen receptor (ER), progesterone receptor (PR), and human epidermal growth factor receptor 2 (HER2). "In line with these previous findings, we revealed that PELI1 acts as an E3 ubiquitin ligase of EGFR to enhance the recycling of EGFR, which accounts for its aberrant expression in triple-negative breast cancers." (PMID 36841821, 2023).
tumor (25 papers, 2013 to 2025). "Collectively, our findings reveal that PELI1 exerts multifaceted roles across pan-cancer, influencing diagnostic accuracy, prognostic outcomes, and the tumor immune microenvironment." (PMID 41562077, 2025). "To test this, we first evaluated the association between PELI1 expression and the abundance of infiltrating immune cell subsets across multiple tumor types." (PMID 41562077, 2025). "Our findings underscore the close association of PELI1 high expression in PC with tumour size and pathological stage." (PMID 38528516, 2024). "Subsequent analysis of clinicopathological characteristics revealed the association between PELI1 expression level and PC tumor size, pTNM stage, T stage, lymphatic metastasis, distant metastasis, vascular invasion, degree of tumor differentiation, and CA19–9." (PMID 38528516, 2024). "Peli1 enhances the stability of the tuberous sclerosis 1 (TSC1)/TSC2 complex in tumor-infiltrating CD8+ T cells by mediating K63-linked TSC1 ubiquitination." (PMID 38179042, 2023). "Accordingly, Peli1 deficiency in T cells leads to a reduction in exhausted tumor infiltrating CD8+ T cells while enhancing their effector functions, thereby establishing antitumor immunity." (PMID 37176148, 2023). "It had been documented that PELI1 plays a protective role in tumor development mainly by regulating K63-linked polyubiquitination of the substrate proteins, including SNAIL/SLUG." (PMID 36841821, 2023). "Peli1 acts as a pathogenic agent in most tumors, where it promotes tumor cell migration and proliferation and negatively affects antitumor immunity." (PMID 38179042, 2023). "Based on these, we propose a dual mechanism through which PELI1 fosters an immunosuppressive TIME: by facilitating the development of immunosuppressive M2-type tumor-associated macrophages (TAMs) in myeloid cells and directly instigating T cell anergy in lymphocytes." (PMID 41562077, 2025). "Hence, Peli1-deficient T cells exhibit high metabolic activities, especially glycolysis, resulting in decreased tumor growth, and increased tumor-infiltrating T cells with stronger antitumor function." (PMID 37176148, 2023). "However, the results of volume analysis showed that the tumor sizes in the Peli1‐deficient mice were significantly larger than those in the WT mice (4.83 ± 2.03 vs 20.23 ± 4.62, P = 0.012)." (PMID 34738714, 2022). "In addition, we found that PELI1 mRNA overexpression was associated with larger tumor size and lymph node metastasis, which consistent with the results from TCGA database that upregulation of PELI1 in PTC patients was closely associated with Ki-67 and lymph node metastasis." (PMID 34991623, 2022). "Conversely, Peli1-cKO in Th17 cells mitigated the tumor-promoting effects of Traf3-cKO and improved Th17 cell differentiation." (PMID 40436857, 2025). "Next, we integrated LIHC tumor expression data from TCGA to identify the top 100 genes showing significant correlation with PELI1 in LIHC." (PMID 41562077, 2025). "Conditional KO of Peli1 (Peli1-cKO) in Th17 cells curbed tumor growth, improved prognosis, and increased Th17 cell infiltration." (PMID 40436857, 2025). "In LIHC specifically, PELI1 expression was significantly elevated compared to adjacent non-tumor tissues." (PMID 41562077, 2025). "Second, future investigations employing in vivo models, such as xenograft experiments in immunodeficient mice, are essential to validate the impact of PELI1 on LIHC tumor growth and metastasis in a complex organismal context." (PMID 41562077, 2025). "PELI1 was frequently overexpressed across multiple tumor types and mainly correlated with poor patient prognosis." (PMID 41562077, 2025). "To further explore the clinical implications of this relationship, we investigated how PELI1 expression and immune cell infiltration jointly impact tumor survival." (PMID 41562077, 2025).
tumor (continued). "To explore the relationship between PELI1 expression and these immunotherapy-relevant biomarkers, we analyzed correlations across tumor types." (PMID 41562077, 2025). "Upon entry into macrophages, miR-21 can suppress the production of PELI1, and less PELI1 in macrophages in the presence of tumor cells or tumor cell-derived stimuli hinders the development of an M1-like phenotype." (PMID 38470169, 2024). "Factors influencing the prognosis of PC patients included gender, tumor size, pTNM stage, T stage, lymphatic metastasis, distant metastasis, vascular invasion, and PELI1 immunohistochemistry (IHC) staining score." (PMID 38528516, 2024). "Peli1 plays a pivotal role in tumors, with complex roles across different cancer types, impacting tumor behavior, therapeutic response, and immune modulation." (PMID 38179042, 2023). "In keeping with previous studies, either PELI1 knockdown or Gefitinib treatment inhibited the ability of the migration, invasiveness and tumor spheres formation of MDA-MB-231 cells, which were further strongly enhanced by the combined treatments." (PMID 36841821, 2023). "Peli1 promotes tumor progression and sensitivity to radiotherapy in papillary thyroid and esophageal squamous carcinomas." (PMID 38179042, 2023). "To further confirm that PELI1‐mediated IR‐mediated tumor cell apoptosis in mice, we collected the tumor tissue of IR‐treated tumor‐bearing mice and performed TUNEL immunofluorescence staining." (PMID 34738714, 2022). "In this study, we presented the first evidence that both mRNA and protein levels of PELI1 widely upregulated in PTC tumor samples." (PMID 34991623, 2022). "Correspondingly, knockdown of NIK significantly inhibited IR‐induced activation of the non‐canonical NF‐KB signaling pathway in PELI1‐knockdown tumor cells, manifested by the inhibition of RelB and p52 nuclear translocation upon IR treatment." (PMID 34738714, 2022). "After undergoing effective radiation therapy, tumor apoptosis was detected by the 18F‐ML‐10 PET/CT scan, and the WT mice showed much higher 18F‐ML‐10 uptake than did the Peli1‐deficient mice (0.31 ± 0.01 vs 0.22 ± 0.01, P = 0.002)." (PMID 34738714, 2022). "More importantly, PELI1 knockdown inhibited tumor growth in subcutaneous tumor model accompanied with the decreased expression of Ki-67 and cell metastasis marker MMP2." (PMID 34991623, 2022). "To confirm PELI1 function in vivo, we subcutaneously inoculated the PELI1‐knockdown or control cells into nude mice and then treated the tumor‐bearing mice with radiotherapy." (PMID 34738714, 2022). "Both mRNA and protein expression of PELI1 were widely increased in PTC tissues, and overexpression of PELI1 was positively correlated with bigger tumor size and lymph node metastases." (PMID 34991623, 2022). "To confirm the Bcl‐XL function in PELI1‐mediated apoptosis during radiotherapy, we reduced Bclxl expression in control and PELI1‐knockdown tumor cells." (PMID 34738714, 2022). "The results revealed that the tumor size was bigger, and apoptotic signaling activation was impaired in the PELI1‐knockdown TE‐1‐tumor–bearing mice that had undergone two rounds of radiotherapy as compared to the control TE‐1‐tumor–bearing mice." (PMID 34738714, 2022). "Consistent with the mRNA levels, the PELI1 protein levels were higher in PTC tissues than in adjacent non-tumor tissues, and PELI1 was predominantly localized in the nucleus and cytoplasm of PTC cells based on IHC." (PMID 34991623, 2022). "Collectively, these findings suggest that m6A regulators may modulate tumor progression across multiple cancer types by regulating PELI1 expression." (PMID 41562077, 2025).
tumor (continued). "To validate this association, we analyzed PELI1 expression across 12 HCCDB datasets (HCCDB 1, 3, 4, 6, 7, 11, 12, 13, 15, 16, 17, and 18), which revealed consistent upregulation of PELI1 in HCC tissues relative to adjacent non-tumor tissues." (PMID 41562077, 2025). "Dysregulated PELI1 expression in tumor tissues implies its involvement in oncogenesis." (PMID 41562077, 2025). "In this study, we systematically performed a comprehensive analysis of PELI1 across multiple tumor types using publicly available datasets to elucidate its expression patterns, clinical relevance, and oncogenic mechanisms, with further in-depth validation in LIHC." (PMID 41562077, 2025). "Given PELI1’s potential role as an oncogene in LIHC, we next examined its association with immune checkpoints molecules, which are key regulators of T cell activation and tumor immune evasion." (PMID 41562077, 2025). "Complementing these transcriptomic data, immunohistochemical results from the Human Protein Atlas (HPA) further corroborated this pattern, with protein expression levels of PELI1 aligning with the gene expression trends observed in both tumor and normal tissues." (PMID 41562077, 2025). "We next tested whether the administration of tumor cell-derived exosomes influences the expression of PELI1 in macrophages." (PMID 38470169, 2024). "Silencing Peli1 reduces tumor migration, invasion, and tumor-sphere formation." (PMID 38179042, 2023). "Conversely, Peli1-mediated K63-linked ubiquitination of IRAK1 and STAT1 activation inhibits IL-10-induced polarization of M2c macrophages and IL-10 production, thereby inhibiting tumor growth." (PMID 38179042, 2023). "Second, Peli1 overexpression upregulates the expression of the apoptosis-inhibitory proteins cIAP1 and cIAP2, conferring resistance to cisplatin- and paclitaxel-induced apoptosis in tumor cells." (PMID 38179042, 2023). "Interestingly, knockdown of Bclxl significantly enhanced IR‐induced tumor cell apoptosis and abolished the apoptosis‐resistant effect in PELI1‐knockdown cells." (PMID 34738714, 2022). "In addition, knockdown of NIK dramatically promoted IR‐induced cleavage of caspase 9, caspase 7, caspase 3, and PARP in PELI1‐knockdown tumor cells, which was consistent with the apoptosis flow cytometry assay results." (PMID 34738714, 2022). "Collectively, these data establish PELI1 as a tumor intrinsic regulator of IR‐induced apoptosis." (PMID 34738714, 2022). "Our findings identify PELI1 as a crucial regulator of tumor radiosensitivity in patients with ESCC." (PMID 34738714, 2022). "However, contradictory results regarding PELI1 expression and its roles in esophageal squamous cancer have been described recently, perhaps mainly because of differences in tumor types, tumor microenvironments, animal model and so on." (PMID 34991623, 2022). "Moreover, IR‐induced NIK accumulation was also dramatically promoted in tumor tissue from 4‐NQO–treated Peli1‐KO mice as compared with that in WT mice." (PMID 34738714, 2022). "Therefore, Bclxl or NIK knockdown abolished the apoptosis‐resistant effect in PELI1‐knockdown tumor cells after radiotherapy." (PMID 34738714, 2022). "Then, the expression of miR-30c-5p and PELI1 in the tumor tissues were determined using real-time PCR, and we found that compared with the NC-EV group, the expression of miR-30c-5p was significantly upregulated, whereas the level of PELI1 was downregulated in the miR-30c-5p-EV group." (PMID 34991623, 2022). "In addition, PELI1 is also involved in T cell metabolism and anti-tumor immunity, and regulates T cell infiltration.These roles of PELI1 may also contribute to the poor results of immunotherapy for PC." (PMID 38528516, 2024). "Therefore, the regulation of glycolysis by Peli1 in the tumor microenvironment and different cell types may involve additional pathways that warrant further in-depth investigation." (PMID 38179042, 2023).